IGHV4-4 (immunoglobulin heavy variable 4-4)
Description:
V region of the variable domain of immunoglobulin heavy chains that participates in the antigen recognition. Immunoglobulins, also known as antibodies, are membrane-bound or secreted glycoproteins produced by B lymphocytes. In the recognition phase of humoral immunity, the membrane-bound immunoglobulins serve as receptors which, upon binding of a specific antigen, trigger the clonal expansion and differentiation of B lymphocytes into immunoglobulins-secreting plasma cells. Secreted immunoglobulins mediate the effector phase of humoral immunity, which results in the elimination of bound antigens. The antigen binding site is formed by the variable domain of one heavy chain, together with that of its associated light chain. Thus, each immunoglobulin has two antigen binding sites with remarkable affinity for a particular antigen. The variable domains are assembled by a process called V-(D)-J rearrangement and can then be subjected to somatic hypermutations which, after exposure to antigen and selection, allow affinity maturation for a particular antigen.
Synonyms: IGHV44; VH
Gene: Immunoglobulin variable (V) gene on chromosome 14 (106,011,922 to 106,012,420, reverse strand). Ensembl gene ENSG00000276775.
Subcellular location: Secreted; Cell membrane
Gene Ontology:
Molecular function: antigen binding
Biological process: immunoglobulin mediated immune response
Cellular component: extracellular region; plasma membrane
Genetic constraint (gnomAD): Missense variants: 158 observed, 60.86 expected, observed/expected ratio (o/e) 2.6. Synonymous variants: 60 observed, 21.87 expected, observed/expected ratio (o/e) 2.74.
Homologues: Paralogues in human: IGHV4OR15-8 (97% identical), IGHV4-59 (92% identical), IGHV4-61 (92% identical), IGHV4-28 (91% identical), IGHV4-31 (91% identical), IGHV4-39 (91% identical), IGHV4-34 (88% identical), IGHV6-1 (62% identical), IGHV3-11 (56% identical), IGHV2-26 (54% identical), IGHV3-23 (54% identical), IGHV3-7 (54% identical), and 65 more.